TMEM275 (transmembrane protein 275)
Gene: Protein-coding gene on chromosome 1 (46,532,166 to 46,544,566, reverse strand). Ensembl gene ENSG00000282881.
Subcellular location: Membrane
Gene Ontology:
Cellular component: membrane
Homologues: Orthologues: chimpanzee TMEM275 (98% identical), macaque TMEM275 (89% identical), rabbit TMEM275 (82% identical), pig TMEM275 (76% identical), mouse Tmem275 (71% identical), rat Tmem275 (69% identical), tropical clawed frog TMEM275 (47% identical), zebrafish tmem275a (45% identical), zebrafish tmem275b (35% identical).